ARID1A (AT-rich interaction domain 1A)
Diseases named in the same sentence as ARID1A in open-access papers (continued):
Sharing a sentence is not in itself a finding about the gene and the disease.
tumor (continued). "ARID1A functions primarily as a tumor suppressor in most of these tumor types; in the absence of ARID1A, defects in control of enhancer activity impair developmental programs and cause extensive dysregulation of gene expression, thus driving tumor formation." (PMID 35125107, 2022). "As a clear driver for the NEC-like SMARCA4/ARID1A molecular tumor class was not apparent in the available retrospective data, we performed whole exome (n = 9) or NGS panel sequencing (n = 10) of 19 tumors from this group." (PMID 36443295, 2022). "In tumor genomes, AKT2 alterations significantly co-occur with ARID1A alterations (OR = 2.0, FDR<0.1% in MSK-IMPACT cohort of 10,945 samples;52 replicated at OR = 1.4, FDR<0.1% in an independent TCGA pan-cancer cohort of 10,967 samples; analysis via cBioPortal53)." (PMID 35614096, 2022). "In contrast to limited metastatic incidences observed in 3-month-old Pten/Arid1a DKO mice, metastatic spreading of tumor cells to distant organs, including the lymph nodes and lungs, was found with high penetrance in PtenPC−/−; Arid1aPC−/− mice at 4 months of ages." (PMID 36435834, 2022). "In this study, mutations in the genes ARID1A, APC, ERBB4, NCOR1, PDGFRA, ATM, and CDKN2A were either non-recurrent or of very low frequency, while none of the 14 sequenced EP tumours harboured mutations in the genes HRAS, EGFR, or RB1." (PMID 34045664, 2022). "ARID1A- correlates with tumor aggressiveness and is a negative prognostic marker of treatment outcome." (PMID 36249060, 2022). "The ATP-TCA assay shows that the ATR inhibitor VE-822 has tumor suppression rates by a factor of about 5 higher in ARID1A negative compared to ARID1A positive CRC cells." (PMID 36249060, 2022). "ARID1A, a subunit of the switch/sucrose nonfermentable chromatin remodeling complex, has emerged as a bona fide tumor suppressor and is frequently downregulated and inactivated in multiple human cancers." (PMID 35611248, 2022). "The comparison of whole-genome sequencing and whole-exome sequencing analyzes of Asian and Caucasian patients shows that there are substantial differences in the molecular tumor characteristics such as the alteration rate of important driver genes such as APC, ARID1A, PTEN and PIK3CA." (PMID 35326507, 2022). "In this study, first we demonstrated that ARID1A depletion is not sufficient to initiate endometrial tumorigenesis, although ARID1A has been described as a driver gene in colon or ovarian neoplasms." (PMID 35167193, 2022). "All studies indicate that ARID1A is low or absent in CRC, and ARID1A acts as a tumor suppressor, which is consistent with the function of ARID1A in other types of cancer." (PMID 35421925, 2022). "Cells from primary tumors with and without ARID1A expression were tested in an ATP-based tumor chemosensitivity assay (ATP-TCA)." (PMID 36249060, 2022). "No significance difference in the expression of ARID1A was found between groups with age, gender, tumor location, histological grade, and N stage." (PMID 34805154, 2021). "The altered tumor microenvironment immune cell populations in ARID1A-induced T-lymphocyte dysfunction have not been tested in the current report." (PMID 34414106, 2021). "Several subunits of the SWI/SNF complex including SNF5 (SMARCB1/INI1/BAF47), ARID1A (BAF240A), SMARCA4 (BRG1), ARID1B (BAF250B), ARID2 (BAF200) and PBRM1 (BAF180) exert critical tumor suppression activities, through inhibiting oncogenic transcription, cell cycle, epigenetic instability and etc.." (PMID 33670012, 2021).
tumor (continued). "The expression of ARID1A impacted the biological functions, including migration, invasion and sphere formation activity, of CHOL and was confirmed to exhibit a tumour-suppressive effect through the regulation of ALDH1A1, a stemness marker, with histone acetylation." (PMID 35127746, 2021). "Moreover, KMT2D positively regulates the enhancer of the tumor suppressor gene IGFBP5 for melanoma suppression and the enhancers of several tumor suppressor genes (e.g., Socs3, Asxl1 and Arid1A) for lymphoma suppression." (PMID 34194626, 2021). "We created the Neo-fs index—defined as the number of marker proteins with low expression among the five independent prognosticators (APC, NOTCH1, ARID1A, EYS, and filamin A)—to develop a simple, practical biomarker with potential prognostic or predictive value reflective of tumor biology." (PMID 33801954, 2021). "Arid1a protein and other SWI/SNF subunits are thought to act as tumor suppressors." (PMID 33869007, 2021). "ARID1A-positive tumors were more likely to be histologically of high grades, ERβ-positive, HNF1β-negative and E-cadherin-negative than ARID1A-negative tumors, but without difference of age, parity, tumor stage and cancer-specific survival." (PMID 33758607, 2021). "A comparative analysis of EBER-ISH and ARID1A immunohistochemistry demonstrated that lost ARID1A was observed in the non-neoplastic mucosa adjacent to the tumor." (PMID 34469459, 2021). "Although ARID1A expression did not associate with BrC molecular subtype, HER-2+ (non-luminal) tumours depict higher ANXA1 protein levels (p < 0.001) than luminal B-like (HER-2+) tumours." (PMID 33276477, 2020). "The tumor of origin of patient 3392 tests positive for Napsin A, and tests negative for estrogen receptor (ER), progesterone receptor (PR), WT1, and ARID1A, suggesting that the tumor was not of endometrial origin." (PMID 32784519, 2020). "These authors reported that ARID1A expression loss was not related to MSI status, TNM stage, pathologic differentiation, tumor location and tumor size." (PMID 32334542, 2020). "Only nine patients presented recurrent tumours within this time period, and neither ARID1A nor ANXA1 expression predicted trastuzumab resistance in this group of BrC patients." (PMID 33276477, 2020). "IHC analysis revealed that ARID1A protein expression was negative in 7 out of 18 (38.8%) tumor tissues when compared with adjacent non-malignant counterparts." (PMID 32334542, 2020). "We were not able to detect a correlation between morphological aspects of the tumour or grading and ARID1A status (data not shown)." (PMID 31906887, 2020). "Taken together, these data suggest that ARID1A may affect the TGF-β axis, which in turn contributes to tumor cell infiltration into and through the myometrial wall, a critical step in metastasis." (PMID 32483112, 2020).
tumor (continued). "Furthermore, ARID1A-low subtype remained as significant predictor when AFP level and tumor size were included in multivariate analysis (HR 1.413, CI 1.234-1.619, p < 0.01)." (PMID 32878261, 2020). "Accumulating data have implicated ARID1A as a key member of the switching defective/sucrose non-fermenting (SWI/SNF) complex, which acts as a tumor suppressor in a broad spectrum of human cancers." (PMID 32878261, 2020). "It has also been reported that defects in ARID1A and dysregulation of the PI3K pathway may have a combined effect on tumor development." (PMID 32508039, 2020). "Beclin-1, ARID1A, CA9 and IDH1 were highly expressed in ICC tumor tissues." (PMID 30849962, 2019). "ARID1A and PTEN are important tumor suppressors in various cancers." (PMID 31241714, 2019). "Among the non-MSI-tumours (i.e. the approximated EBV-positive, GS and CIN subtypes), ARID1A protein loss was more frequent in the approximated GS subtype (5/24 of GS cases, 20.8%), in line with the TCGA study results." (PMID 31790410, 2019). "In the absence of ARID1A, the proliferation of these cells is severely impaired, suggesting a tumor-supporting function in this context." (PMID 31217031, 2019). "The ARID1 subfamily includes ARID1A and ARID1B, two subunits of the SWI/SNF chromatin remodeling complex, and data suggest that ARID1A may act as a tumor suppressor." (PMID 31126056, 2019). "Stratification by tumor differentiation showed that ARID1A negativity had no impact on prognosis in differentiated cases in the test cohort (P = 0.442)." (PMID 31043675, 2019). "Since the role of ARID1A has not been explored in NSCLC, we investigated how ARID1A deficiency affected tumor microenvironment and immune landscape in these patients." (PMID 30400822, 2018). "Statistical analysis showed that the average expression level of ARID1A in tumor tissues was significantly lower than that in surrounding noncancerous tissues." (PMID 29317648, 2018). "In clinical samples miR-223 is upregulated in the tumor, while ARID1A is downregulated significantly in comparison to the non-tumor adjacent mucosa from the same patients." (PMID 29675003, 2018). "We identified seven oncogenes (NRAS, EGFR, RXRA, HRAS, KRAS, AKT1, ERBB2; q<0.10) and seven putative tumor suppressor genes (ARID1A, TXNIP, CTNNB1, PIK3RI, CDKN2A, KLF5, STAG2; q<0.10) significantly regulated between tumor and control, which were formerly reported to be altered in BC." (PMID 30419021, 2018). "In concordance with this notion, ARID1A knockout alone did not result in tumor formation in the murine urinary bladder." (PMID 30138427, 2018). "Interestingly, in a mutant mouse model of ARID1A dependent OCCC, concurrent activation of PIK3CA was required for tumor formation, suggesting that the SWI/SNF chromatin remodeling and PI3K pathways converge in the development of OCCC." (PMID 28611940, 2017). "Furthermore, knockdown of ARID1A was able to sensitise human cancer cell lines to VE-821 and VX-970 in vitro and mice with HCT116 xenograft tumours in vivo." (PMID 28448462, 2017). "Research in the mechanism of miR-31 found that it could target genes such as ARID1A, SATB2, ARID1A, HuR, BAP1, EZH2, and RASA1, and it could further activate oncogenes and promote tumor cell proliferation, migration and invasive capability in vitro." (PMID 28404921, 2017). "HIC1 is a tumor suppressor and a transcriptional repressor, which inhibits E2F1 transcription through the recruitment of SWI/SNF complex by a direct interaction with ARID1A." (PMID 27323812, 2016). "ARID1A protein expression was found to be lower in tumor tissue samples compared to paired non-cancerous matched tissues (NCMTs)." (PMID 27528032, 2016).
tumor (continued). "Among tumor samples, ARID1A expression was negative in 27.3% of the tissues whereas cMET and PIK3CA expression was positive in 63.6% and 87.8% of the tumors respectively." (PMID 26334097, 2015). "Finally, we evaluated the role of ARID1A in HCC cell migration and invasion in vitro, and conducted HCC tumor xenograft studies to determine the biological functions of ARID1A in vivo." (PMID 25975202, 2015). "ARID1A is a member of the chromatin-remodeling SWI/SNF complex, which is involved in the regulation of many cellular processes, including differentiation, proliferation, DNA repair, and tumor suppression." (PMID 26544626, 2015). "Although a decreased ARID1A expression was detected in tumor tissues, it did not remain statistically significant (P = 0.52)." (PMID 26334097, 2015). "Strong ARID1A-positive nuclear staining was found in normal tissues, whereas ARID1A-negative staining (dark blue) can be seen in tumor tissues." (PMID 25975202, 2015). "Considering that E-cadherin is essential for cell adhesion, it is possible that decreased ARID1A expression in HCC tissues might loosen cell-cell junctions, promoting the migration and invasive capacity of tumor cells." (PMID 25975202, 2015). "In the same 64 paired HCC samples, immunohistochemical analysis revealed that ARID1A protein expression was decreased in 41 out of 64 (64.1 %) tumor tissues when compared with adjacent non-tumorous counterparts." (PMID 25975202, 2015). "In our study, ARID1A expression was lower in tumor samples compared to control samples although no statistical differences were found." (PMID 26334097, 2015). "ARID1A is a known suppressor of tumour formation and the Human Protein Atlas antibody HPA005456 has been demonstrated in previous literature to stain tumour tissue by immunohistochemistry (IHC) in formalin-fixed paraffin embedded human tissue and human cell lines." (PMID 25653835, 2014). "Moreover, studies have confirmed that ARID1A gene knockdown functionally promoted the proliferation, migration and invasion of HCC cells, suggesting that ARID1A is a tumor suppressor." (PMID 24955791, 2014). "The SNParray technique used in this study identified deletions affecting ARID1A in only one tumor (data not shown)." (PMID 25161957, 2014). "This shows that ARID1A inactivation in itself is not sufficient to initiate tumor development and requires a second hit, possibly consistent with an alteration in the PI3K/PTEN/AKT pathway to lead to carcinogenic transformation." (PMID 24036443, 2013). "In combination with the results of gene expression profiling of these two tumor types, activation of oncogenic KRAS and PI3K survival pathways, and inactivation of tumor suppressor genes PTEN and ARID1A are suggested for clear cell and endometrioid ovarian carcinomas, respectively." (PMID 23466883, 2013). "The ARID1A expression level was significantly lower in 43 (65.15%) tumor-bearing tissues compared with the adjacent non-tumor tissues (P = 0.0029)." (PMID 22808142, 2012). "JUND did not correlate with tumour stage, ARID1A levels, or patient survival." (PMID 39885328, 2025). "Interestingly, cFos levels inversely correlated with ARID1A status, while cFos levels increased as tumour stages increased from Stage 1 to 3, though not in Stage 4 tumours." (PMID 39885328, 2025). "We also found that Arid1a depletion alone could not induce tumour formation in the pancreas, consisting with the results of previous studies and supporting the notion that the interplay between different dysregulated genes are essential for tumour formation." (PMID 40621620, 2025).
tumor (continued). "Significantly, ARID1A loss did not correlate with clinical outcomes, stage, age, or CD8+ tumor-infiltrating lymphocyte (TIL) levels in either histotype, suggesting that while ARID1A mutation is a key molecular event in tumorigenesis, it lacks prognostic significance." (PMID 41425725, 2025). "At clinical endpoint, tumour weights were comparable irrespective of the Arid1a status." (PMID 39885328, 2025). "ARID1A may represent a tumor suppressor gene in pancreatic carcinogenesis, as its expression levels correlate with tumor differentiation and stage, although not with lymph node or distant metastasis, sex, or age." (PMID 38893181, 2024). "According to the tumor weight, RITA inhibited tumor growth with or without ARID1A expression." (PMID 38811536, 2024). "CRISPR-Cas9 KO of ARID1A in ID8 cells investigated in both an intraperitoneal and an orthotopic model showed increased tumour-infiltrating lymphocytes and PD-L1 levels and a greater response to an anti-PD-L1 antibody compared to WT ARID1A tumours, with lower tumour burden and prolonged survival." (PMID 39272926, 2024). "Interestingly, it appears that biallelic inactivation of Arid1a is not necessary to enhance the aggressive phenotype as we observed similar trends of survival and tumor burden between the Arid1afl/fl mice and the Arid1afl/wt mice." (PMID 39123453, 2024). "For example, in a tumor cell without the expression of ARID1A, the elevated methyl transferase activity of EZH2 will suppress the function of Th1-type chemokines and IFN-g-responsive genes by converting H3K27 to H3K27me3 on the Th1-type chemokines and the IFN response promoters." (PMID 37371564, 2023). "However, a small study on OCCC patients found higher expression of PD-L1 and more tumor-infiltrating lymphocytes in tumors with high MSI, but the relationship with ARID1A mutation has not been studied." (PMID 36873929, 2023). "Interestingly, the PFS after ICB therapy was significantly longer in patients with altered ARID1A than in those with wildtype ARID1A, regardless of microsatellite instability (MSI) and tumor mutation burden (TMB) statuses." (PMID 36980292, 2023). "In addition, ARID1A, ARID2, BRG1, and PBRM1 are all bona fide tumor suppressors." (PMID 37371564, 2023). "The enrichment of ARID1A and KMT2D mutations in BCL2 + FL, independent of the clinical stage, might indicate an altered accessibility to the chromatin structure of the tumor cells." (PMID 37563306, 2023). "Similarly, negative immunohistochemical expression of ARID1A has been noted in 66% of either OCCCs or EnOCs developing on endometriotic cysts, as well as in the endometriotic epithelium proximal to the tumor." (PMID 37627318, 2023). "Furthermore, in vitro experiments suggested that ARID1A knockdown (ARID1A-KD) activates the EGFR/PI3K/Akt/mTOR pathway and inhibits tumor cell autophagy, which attenuates inhibition of the Rig-I-like receptor pathway and production of type I interferon (IFN) in EGFR-mutant LUAD cells." (PMID 36229854, 2022). "In contrast to the phenotype observed in mice, Arid1a silencing only slightly enhanced the capacity of tumor cells to form organoids without significant alteration in proliferation, suggesting that TME-mediated mechanisms account for enhanced tumor progression in vivo." (PMID 36435834, 2022). "Within the final interaction network, the type-I–IFN–Response pathway and T cell regulatory showed a major connection with DEGs, indicating that ARID1A may interact with Treg and promote Type-I–IFN–Response pathway to facilitate tumor immune response in EC (e)." (PMID 36281289, 2022).